PRMT5 (protein arginine methyltransferase 5)
Diseases named in the same sentence as PRMT5 in open-access papers (continued):
Sharing a sentence is not in itself a finding about the gene and the disease.
colorectal cancer (56 papers, 2015 to 2026). A primary or metastatic malignant neoplasm that affects the colon or rectum. "In the current study, we uncovered the novel role of PRMT5 in human colorectal cancer and revealed the underlying molecular mechanism by which PRMT5 regulated CRC cell proliferation and EMT." (PMID 33495409, 2021). "It has also emerged that KRAS mutation correlates with higher PRMT5 expression in colorectal cancer and increased susceptibility to PRMT5 inhibition." (PMID 34680285, 2021). "Altogether, our findings indicate that PRMT5 is an ectopic expression in human colorectal cancer, and the PRMT5 enzyme activity is closely linked to colorectal cancer." (PMID 33495409, 2021). "Consequently, understanding the prevalence and significance of PRMT5 mutations holds promise for informing novel therapeutic interventions targeting the molecular underpinnings of skin and colorectal cancer." (PMID 38203325, 2023). "However, the underlying mechanisms by which PRMT5 contributes to the progression of colorectal cancer (CRC) remain to be defined." (PMID 33664859, 2021). "Moreover, the loss of NatD sensitized the colorectal cancer xenograft mice to the 5-fluorouracil treatment to slow the tumor growth through transcriptional downregulation of protein arginine methyltransferase 5 (PRMT5)." (PMID 33435607, 2021). "It has also been demonstrated that Prmt5 knockout can affect the proliferation and survival of B cells, and Prmt-deficient B cells show tumor-protective effects in colorectal cancer; therefore, targeting Prmt5 could regulate the function of B cells in the TME and thereby affect tumor immunity." (PMID 37808922, 2023). "It has been demonstrated that YBX1 methylation mediated by PRMT5 can regulate NF-κB activity in colorectal cancer." (PMID 41507134, 2026). "Consistent with published studies, our study demonstrated that PRMT5 methylates AKT1 at R391 to activate the AKT/mTOR signaling pathway in colorectal cancer cells." (PMID 40279519, 2025). "Accumulating evidence indicates that PRMT5 functions as an oncogene in colorectal cancer and that its cancer‐promoting function depends on its methyltransferase activity, suggesting that PRMT5 is a potential target for cancer therapy." (PMID 40279519, 2025). "Neural precursor cell expressed developmentally down‐regulated gene 4‐like (NEDD4L) prevents colorectal cancer liver metastasis through ubiquitination and degradation of protein arginine methyltransferase 5 (PRMT5)." (PMID 40279519, 2025). "HCT116 MTAP WT and MTAP-/- colorectal cancer cells constitute an isogenic pair which has served as the model system to benchmark synthetic lethal PRMT5 inhibitors." (PMID 41339334, 2025). "In colorectal cancer, PRMT5 facilitates the metastasis of tumor cells through the methylation of SMAD4." (PMID 41463372, 2025). "In colorectal cancer, PRMT5 overexpression can result in the activation of NF- kB via arginine methylation on its p65 subunit, and anticancer therapies are based on targeting such interaction." (PMID 40869229, 2025). "At R361, PRMT5 mechanically triggers Deleted in Pancreatic Cancer 4 methylation, promoting colorectal cancer metastasis." (PMID 38911125, 2024). "PRMT5 is overexpressed and negatively correlated with survival in patients with colorectal cancer and other cancers." (PMID 38000655, 2024). "In colorectal carcinoma, protein arginine methyltransferase 5 (PRMT5) catalyzes methylation of the multifunctional protein Y-box binding protein 1 (YBX1) and causes NF-κB activation, which, in turn, leads to increased cell proliferation in vitro." (PMID 38279330, 2024). "In the intestine, PRMT5 is up-regulated in colorectal cancer and its expression positively correlates with a poorer prognosis." (PMID 37666668, 2023). "PRMT5 is a critical player in various cancer types, including colorectal cancer, and its increased expression is common in these malignancies." (PMID 38203325, 2023).
colorectal cancer (continued). "Cell culture studies suggest that PRMT5 contributes to colorectal cancer cell growth by transcriptionally activating oncogenes and/or repressing tumor suppressive protein functions." (PMID 37666668, 2023). "Recent studies implicate PRMT5 in colorectal cancer pathogenesis, but its physiological roles under homeostasis and enteric pathogen challenges are not known." (PMID 37666668, 2023). "In parallel with the discovery of the PRMT2/4 complex, another group identified PRMT5 and PRMT6 as functionally associating enzymes as oncogenic drivers in colorectal cancer." (PMID 37863263, 2023). "PRMT5 was highly expressed in colorectal cancer tissues compared with their normal counterparts and correlated with poor prognosis in CRC patients." (PMID 36474242, 2022). "In the present study, TCGA data analysis showed an elevated PRMT5 expression in colorectal cancer tissues; this result was further validated in another two GSE datasets and clinical CRC tumor tissues." (PMID 36474242, 2022). "We detected the expression level of PRMT5 and glycolytic enzymes using online databases and colorectal cancer cell lines by immunohistochemical staining, quantitative real-time polymerase chain reaction (qRT-PCR), and western blotting." (PMID 36474242, 2022). "In order to explore the function of PRMT5 in human colorectal cancer, we firstly evaluated the mRNA expression level of PRMT5 in various human colorectal cancer cell lines." (PMID 33495409, 2021). "To further confirm that PRMT5 has participated in human colorectal cancer, we collected human colorectal tumors and adjacent normal tissues from patients." (PMID 33495409, 2021). "Altogether, our findings reveal that PRMT5 controls EMT through activation of the EGFR/Akt/GSK3β signaling pathway in colorectal cancer cells." (PMID 33495409, 2021). "PRMT5 mRNA expression level was markedly increased in those colorectal cancer cell lines compared with normal colonic mucosal FHC cells." (PMID 33495409, 2021). "PRMT5 is overexpressed in many cancers including melanoma, lung, gastric, ovarian, and colorectal cancers." (PMID 34124017, 2021). "We found that phospho-EGFR was significantly impaired, whereas the total EGFR was unchanged, suggesting that PRMT5 regulates EGFR activation in colorectal cancer." (PMID 33495409, 2021). "Further studies show that silencing PRMT5 by shRNA or inhibition of PRMT5 by specific inhibitor GSK591 suppresses colorectal cancer cell growth and cell cycle progression, which is closely related to PRMT5 enzyme activity." (PMID 33495409, 2021). "Taken together, our results suggest that the enzyme activity of PRMT5 is required for colorectal cancer cell proliferation and cell cycle progression." (PMID 33495409, 2021). "More importantly, the new insights into the activation of EGFR/Akt/GSK3β signaling axis medicated by PRMT5 provide much new information for the mechanisms of the carcinogenic effect of PRMT5 in human colorectal cancer." (PMID 33495409, 2021). "In order to explore the role of PRMT5 in human colorectal cancer, we generated the PRMT5 stable knockdown cell lines using lentivirus containing PRMT5 shRNAs and Scramble (Scr)." (PMID 33495409, 2021). "In the current study, we confirm that PRMT5 is frequently highly expressed in human colorectal cancer cells and tissues in both mRNA and protein levels." (PMID 33495409, 2021). "Our findings also pose the possibility that PRMT5 promotes colorectal cancer cell growth, cell cycle progression, and EMT via EGFR/Akt/GSK3β signaling axis." (PMID 33495409, 2021). "The PRMT5 protein expression level was dramatically increased compared to the normal colonic mucosal FHC cells, indicating that PRMT5 is highly expressed in human colorectal cancer cells." (PMID 33495409, 2021). "A previous study has shown that PRMT5 is involved in many types of human cancer and tumor progression, including colorectal cancer." (PMID 33495409, 2021).
colorectal cancer (continued). "In summary, our study provides evidence that PRMT5 is overexpressed in human colorectal cancer cells and tissues." (PMID 33495409, 2021). "In their experiment, PRMT5 knockdown led to decreased eIF4E and FGFR3 gene expression while PRMT5 was overexpressed in colorectal cancer cells, correlating with decreased overall patient survival." (PMID 33440687, 2021). "Collectively, our findings indicate that PRMT5 control human colorectal cancer cell growth and cell cycle progression." (PMID 33495409, 2021). "More importantly, our results also uncover that PRMT5 promotes EMT in colorectal cancer cells via EGFR/Akt/GSK3β signaling axis." (PMID 33495409, 2021). "We showed that phosphorylation of PRMT5 at S15 by protein kinase C iota (PKCι) enhances colorectal cancer cell growth, motility, colony formation, and anchorage-independent growth." (PMID 33375283, 2020). "The overexpression of PRMT5 is highly correlated to poor clinical outcomes for colorectal cancer (CRC) patients." (PMID 32456215, 2020). "We identified three proteins of tumorigenesis: CAV1, KPNA2, and PRMT5 being downregulated by GS treatment in colorectal cancer HCT 116 cells." (PMID 31581454, 2019). "Here, we provide evidence that PRMT5 is overexpressed in colorectal cancer (CRC) cells and patient-derived primary tumors, correlated with increased cell growth and decreased overall patient survival." (PMID 26078354, 2015). "Here, we found that the overexpression of PRMT5 increased the proliferation of colorectal cancer cells and that the effect of PRMT5 on colorectal cancer cell proliferation was reversed by treatment with rapamycin, a selective mTOR inhibitor that suppresses the AKT/mTOR signaling pathway." (PMID 40279519, 2025). "Although functional experiments showed that NEDD4L prevented colorectal cancer liver metastasis through PRMT5 degradation to attenuate the methylation of R391 in AKT1, we did not obtain direct evidence that NEDD4L mediated PRMT5 degradation to attenuate the methylation of R391 in AKT1." (PMID 40279519, 2025). "Moreover, PRMT5 deficiency, as well as the inhibition of PRMT5 by EPZ015666, decreased the proliferation of colorectal cancer cells." (PMID 40279519, 2025). "More recently, PRMT5 is an emerging key target for the treatment of colorectal cancers." (PMID 38000655, 2024). "Additionally, epigenetic alterations, such as N-alpha-acetyltransferase 40 (NAA40)-induced acetylation, have been reported to contribute to PRMT5 overexpression in colorectal cancer." (PMID 38666828, 2024). "Recent studies have suggested that protein arginine N-methyltransferase 5 (PRMT5) could serve as a potential prognostic and therapeutic biomarker in various cancers, including breast, lung, and colorectal cancer." (PMID 38666828, 2024). "PR5-LL-CM01 demonstrated binding affinity to the active site of PRMT5 in silico, and it displayed anti-tumor effects in both in vitro and in vivo systems of pancreatic ductal adenocarcinoma (PDAC) and colorectal cancer (CRC) superior to the commercial inhibitor of PRMT5, EPZ01566627." (PMID 36720900, 2023). "(S)-2-(Cyclobutylamino)-N-(3-(3,4-dihydroisoquinolin-2(1H)-yl)-2-hydroxypropyl)isonicotinamide (EPZ015866) is another PRMT5 specific inhibitor, which blocks the enzyme activity of PRMT5 in the proliferation and cell cycle progression of human colorectal cancer cells." (PMID 36901758, 2023). "In addition, qRT-PCR and IHC staining showed that the expression of LDHA was significantly declined in combination group, establishing that PRMT5 blockade can inhibit the growth of colorectal cancer via the LDHA regulation." (PMID 36474242, 2022). "At present, there are relatively few studies on the relation of PRMT5 with colorectal cancer." (PMID 36474242, 2022). "Our data indicates that PRMT5 promoted colorectal cancer proliferation partially through activating glycolysis and may be a potential target for colorectal cancer therapy." (PMID 36474242, 2022).
colorectal cancer (continued). "Moreover, bioinformation analysis demonstrated that higher LDHA (as well as LDHA and PRMT5 combination) indicated a worse prognosis in colorectal cancer patients." (PMID 36474242, 2022). "Then, we knocked down and overexpressed PRMT5 in colorectal cancer cells respectively." (PMID 36474242, 2022). "Collectively, the results of our present study uncovered a novel PRMT5 role in colorectal cancer, and targeting PRMT5 might be a strategy for the improvement treatment of colorectal cancer." (PMID 36474242, 2022). "Therefore, it is of vital importance to uncover the function of PRMT5 in colorectal cancer with an aim to identify novel prognostic and treatment targets." (PMID 36474242, 2022). "Our results further imply that PRMT5 may act as a novel therapeutic candidate for the treatment of human colorectal cancer." (PMID 33495409, 2021). "Most importantly, our findings also suggest that PRMT5 may be a potential therapeutic target for the treatment of human colorectal cancer." (PMID 33495409, 2021). "Moreover, Western blot analysis showed that PRMT5 protein expression level was distinctly elevated as well, implying that PRMT5 plays an essential role in human colorectal cancer development and progression." (PMID 33495409, 2021). "Finally, our findings reveal that PRMT5 promotes EMT through activation of the EGFR/Akt/GSK3β signaling pathway in colorectal cancer cells." (PMID 33495409, 2021). "It has been reported that PRMT5 regulates colorectal cancer cell growth via ERK signal cascades." (PMID 33495409, 2021). "The phospho-Thr308 and phospho-Ser473 Akt expression level was remarkably decreased when PRMT5 was down-regulated in HCT116 and SW480 cells, implying that PRMT5 controlled colorectal cancer cell proliferation and cell cycle progression through regulation of Akt activity." (PMID 33495409, 2021). "Nevertheless, it is completely unknown whether PRMT5 is engaged in human colorectal cancer cell proliferation and EMT." (PMID 33495409, 2021). "Although PRMT5 is participated in human colorectal cancer, how PRMT5 gates the tumor cell growth and epithelial-mesenchymal transition (EMT) and the related molecular mechanisms are still entirely unknown." (PMID 33495409, 2021). "However, the precise role and function of PRMT5 in human colorectal cancer (CRC) growth and epithelial-mesenchymal transition (EMT) are still unclear, and the related molecular mechanism and signaling axis remains largely obscure." (PMID 33495409, 2021). "Interestingly, our group recently delineated the relationship between the transcription factors YBX1, NF-κB, and PRMT5 in colorectal cancer." (PMID 33375283, 2020). "However, the detailed mechanism of PRMT5 promoting colorectal cancer (CRC) malignant progression remains unclear." (PMID 39781264, 2025). "Similarly, PRMT5 knockout prevented colorectal cancer liver metastasis." (PMID 40279519, 2025). "We previously showed that PRMT5 methylates and activates a proangiogenic and proinflammatory transcription factor, the nuclear factor kappa B (NF-κB), which has a master role in tumor progression, notably in pancreatic ductal adenocarcinoma and colorectal cancer." (PMID 36720900, 2023). "In conclusion, PRMT5 could potentially regulate aerobic glycolysis in colorectal cancer." (PMID 36474242, 2022). "Observations revealed that the tumor volume and mass of nude mice were remarkably reduced after administrated with tadalafil and 5-FU combination, indicating that blockade of PRMT5 activity could inhibit the cell growth and increase the efficacy of 5-FU in colorectal cancer cells." (PMID 36474242, 2022). "However, the role of PRMT5 in colorectal cancer remains poorly understood." (PMID 36474242, 2022). "Next, we further evaluated whether PRMT5 was engaged in colorectal cancer." (PMID 33495409, 2021).
colorectal cancer (continued). "Although previous studies have shown that PRMT5 may regulate Akt activity via control of PI3K hyperphosphorylation or PTEN hypophosphorylation in cancer cells, how PRMT5 promotes colorectal cancer cell growth and EMT and the underlying molecular mechanism is still undiscovered." (PMID 33495409, 2021). "Meng found that protein arginine methyltransferase 5 (PRMT5) promotes B7-H3 expression by mediating the m6A modification of its mRNA via meR316-ALKBH5, impacting colorectal cancer (CRC) prognosis." (PMID 40519928, 2025). "Similar correlations between PRMT5 and FGFR3 or PI3K/AKT/mTOR and ERK signaling have been reported in non-small cell lung cancer and colorectal cancer cell lines." (PMID 40791817, 2025). "The interaction and methylation of SMAD4 by the oncogene protein arginine methyltransferase 5 (PRMT5) are essential for driving TGF-β1-induced EMT and promoting metastasis in colorectal cancer (CRC)." (PMID 40109873, 2025). "This study is the first to show that PRMT5 is a substrate of NEDD4L and reveals not only the metastasis‐inhibiting function of NEDD4L but also a novel mechanism by which NEDD4L prevents colorectal cancer liver metastasis." (PMID 40279519, 2025). "NEDD4L knockdown stabilized PRMT5, resulting in the arginine methylation of AKT1, whereas the overexpression of NEDD4L‐R in NEDD4L‐knockdown colorectal cancer cells promoted PRMT5 degradation to attenuate AKT1 methylarginine levels." (PMID 40279519, 2025). "In colorectal cancer (CRC) tissues, the expression of eIF4E is positively correlated with PRMT5, silencing PRMT5 leads to decreased eIF4E expression." (PMID 37601696, 2023). "In addition, several studies indicated that PRMT5 promoted colorectal cancer progress; however, the role of PRMT5 in colorectal cancer remains unclear, and the molecular mechanism of PRMT5 in the regulation of CRC cell growth and the related signaling axis is entirely unknown." (PMID 36474242, 2022). "As we have previously shown in colorectal cancer, PRMT1 and PRMT5 expression can be upregulated both in colonic tumors and adjacent tissue." (PMID 34439753, 2021). "MCM7 was identified as a direct target of PRMT5 in colorectal cancer, and both MCM7 and PRMT5 were up-regulated in CRC tissue and promoted cell proliferation, migration and invasion." (PMID 34859821, 2021). "A previous study showed elevated expression of CORO2A in colorectal carcinoma tissues, and a link between its expression and oncogenic MAPK14 and PRMT5 signaling pathways." (PMID 34884487, 2021). "Further evidence in support of the activator role played by PRMT5 comes from studies of the Fibroblast-derived Growth Factor Receptor-3 (FGFR-3) and eukaryotic elongation Initiation Factor-4E (eIF4E) genes in colorectal cancer." (PMID 30613353, 2018). "Collectively, our findings support the hypothesis that in liver‐metastatic colorectal cancer cells, NEDD4L binds to the PPNAY motif in PRMT5, resulting in the ubiquitination and degradation of PRMT5." (PMID 40279519, 2025). "Moreover, PRMT5‐mediated methylation of AKT1 at R391 increased cell proliferation to enhance colonization, in turn promoting colorectal cancer liver metastasis." (PMID 40279519, 2025). "Furthermore, PRMT5 functionally interacts with EZH2 to suppress CDKN2B expression through epigenetic mechanisms, promoting colorectal cancer (CRC) progression." (PMID 39043634, 2024). "We therefore examined the effect of pharmacological inhibition of PRMT5 activity using a small molecule active site inhibitor, T1-44, which is an effective and selective inhibitor of PRMT5 in murine CT26 colorectal cancer (CRC) cells." (PMID 36841868, 2023). "Here, PRMT5 was found to be upregulated in colorectal cancer and could promote cell proliferation by transcriptionally activating LDHA to enhance aerobic glycolysis, suggesting that PRMT5 may be a potential therapeutic target for colorectal cancer." (PMID 36474242, 2022).